CEP152 (centrosomal protein 152)
Description:
Necessary for centrosome duplication; the function also seems to involve CEP63, CDK5RAP2 and WDR62 through a stepwise assembled complex at the centrosome that recruits CDK2 required for centriole duplication. Acts as a molecular scaffold facilitating the interaction of PLK4 and CPAP, 2 molecules involved in centriole formation. Proposed to snatch PLK4 away from PLK4:CEP92 complexes in early G1 daughter centriole and to reposition PLK4 at the outer boundary of a newly forming CEP152 ring structure. Also plays a key role in deuterosome-mediated centriole amplification in multiciliated that can generate more than 100 centrioles (By similarity). Overexpression of CEP152 can drive amplification of centrioles.
Synonyms: KIAA0912; SCKL5; MCPH9; MCPH4
Tractability: PROTAC: ubiquitination databases record sites on it.
Gene: Protein-coding gene on chromosome 15 (48,712,928 to 48,811,146, reverse strand). Ensembl gene ENSG00000103995.
Subcellular location: Cytoplasm, cytoskeleton, microtubule organizing center, centrosome; Cytoplasm, cytoskeleton, microtubule organizing center, centrosome, centriole
Subcellular location (Human Protein Atlas): Basal body; Centrosome; Nucleoplasm
Pathways (Reactome):
Cell Cycle: AURKA Activation by TPX2; Loss of Nlp from mitotic centrosomes; Loss of proteins required for interphase microtubule organization from the centrosome; Recruitment of NuMA to mitotic centrosomes; Recruitment of mitotic centrosome proteins and complexes; Regulation of PLK1 Activity at G2/M Transition
Organelle biogenesis and maintenance: Anchoring of the basal body to the plasma membrane
Gene Ontology:
Molecular function: protein binding; protein kinase binding; protein-macromolecule adaptor activity
Biological process: centriole replication; centrosome duplication; de novo centriole assembly involved in multi-ciliated epithelial cell differentiation
Cellular component: centriole; centrosome; ciliary basal body; pericentriolar material; procentriole; procentriole replication complex; cytosol; deuterosome
Genetic constraint (gnomAD): Loss-of-function variants: 120 observed, 178.1 expected, observed/expected ratio (o/e) 0.67, 90% interval 0.58 to 0.78. The upper end of that interval is the gene's LOEUF score, 0.78, which puts it in group 3 of 6, group 1 being the genes least tolerant of losing a copy. Missense variants: 1,808 observed, 1,956.8 expected, observed/expected ratio (o/e) 0.92, 90% interval 0.89 to 0.96. Synonymous variants: 618 observed, 669.21 expected, observed/expected ratio (o/e) 0.92, 90% interval 0.86 to 0.99.
Gene-disease validity (ClinGen):
ClinGen rates the evidence that CEP152 causes each of these diseases.
microcephaly with or without short stature (autosomal recessive): Definitive. Primary microcephaly refers to the clinical finding of a head circumference more than than 3 standard deviations (SD) below the age- and sex-related mean, present at birth.
Homologues: Orthologues: chimpanzee CEP152 (99% identical), macaque CEP152 (95% identical), dog CEP152 (82% identical), rabbit CEP152 (80% identical), pig CEP152 (80% identical), mouse Cep152 (65% identical), rat Cep152 (65% identical), guinea pig CEP152 (65% identical), tropical clawed frog cep152 (40% identical), zebrafish cep152 (30% identical). Paralogues in human: SHC4 (6% identical), SHC1 (6% identical), SHC3 (6% identical).
Diseases named in the same sentence as CEP152 in open-access papers:
CEP152 is named in the same sentence as 24 diseases in open-access papers, as found by Europe PMC text mining. Sharing a sentence is not in itself a finding about the gene and the disease. The quoted sentences say what the papers report.
microcephaly (26 papers, 2012 to 2026). A congenital or acquired developmental disorder in which the circumference of the head is smaller than normal for the person's age and sex. "Collectively, these findings demonstrate that distinct CEP152 variants disrupt neurodevelopment through different mechanisms, thereby explaining the spectrum of microcephaly severity and associated phenotypes." (PMID 42086905, 2026). "CEP152 variants are established causes of both microcephaly and Seckel syndrome phenotypes, but the pathogenicity of different variant combinations and their clinical recurrence patterns require further verification with additional cases." (PMID 41306914, 2025). "The autosomal recessive primary microcephaly syndrome gene MCPH4 was originally defined as a microcephaly linkage region on chromosome 15q15-21, where a microcephaly-inducing mutation in the centrosomal CEP152 gene was initially identified." (PMID 31878213, 2019). "The CEP152 gene is localised to the MCPH4 locus at chromosome 15q21.1; recently, microcephaly due to a mutation in the CEP152 gene was designated as MCPH9." (PMID 25951892, 2015). "CEP63 was demonstrated to play a key role in the recruitment of CEP152, another centrosomal protein implicated in microcephaly, to centrosomes and the artificial tethering of CEP152 to centrosomes rescued many of the cellular phenotypes of CEP63 mutant cells." (PMID 23532176, 2013). "However, molecular mechanisms for microcephaly mutations in centrosomal proteins, such as Cep135, Cep152, and WDR62, remain clouded." (PMID 38857398, 2024). "Based on the Human Gene Mutation Database (HGMD), 32 variants in CEP152 have been identified in patients and have reported to be associated with different kinds of diseases including microcephaly, Seckel syndrome, atrioventricular septum defect, and autism spectrum disorder." (PMID 36685824, 2022). "Additionally, the digenic inheritance of CDK5RAP2 and CEP152 heterozygous mutations causes Seckel syndrome, a disease which includes microcephaly as a clinical feature." (PMID 33178111, 2020). "Interestingly, different mutations in the centrosomal proteins CENPJ or CEP152 can cause microcephaly or Seckel syndrome." (PMID 23166506, 2012). "Moreover, mutations in Cep63 or Cep152 that disrupt Cep63•Cep152 self-assembly result in impaired centriole duplication, which could lead to chromosome missegregation and yield genetic disorders such as cancer, microcephaly, ciliopathy, and dwarfism." (PMID 37433832, 2023). "Mutations in two of them, CENPJ and CEP152, could also cause an allelic condition known as autosomal recessive Seckel syndrome, which is characterized by proportionate growth and mental retardation, microcephaly, and characteristic bird-like face." (PMID 29504900, 2018). "This is further supported by the fact that many genes associated with microcephaly encode centrosome proteins (CPAP, CEP152, CEP135, STIL, and CDK5RAP2) involved in centriole biogenesis and centrosome maturation." (PMID 39412222, 2025). "All common mutations causing microcephaly are present in genes implicated in cell division (MCPH1, ASPM, CDK5RAP2, CENPJ, STIL, WDR62, and CEP152)." (PMID 37294214, 2023). "It has been also shown that CEP63 forms a complex with CEP152, another centrosomal protein implicated in microcephaly, and CEP63 deficiency leads to centriole loss due to impaired recruitment of CEP152 to the centrosome." (PMID 35805981, 2022). "Not surprisingly, mutations in Cep63 and Cep152 are associated with the development of human diseases, such as microcephaly and primordial dwarfism." (PMID 32810424, 2020). "We observed one single m6A site near the stop codon in 7 microcephaly-related E-SMRs, including Brca2, Cep152, Ddx11, Nde1, Kif14, Stil and Cdk5rap2, 3 polymicrogyria-related E-SMRs (Eomes/Tbr2, Pax6 and Foxp2), and 3 megalencephaly-related E-SMRs (Gli3, Ccnd2 and Kif7)." (PMID 32992647, 2020).
microcephaly (continued). "We hypothesize that microcephaly-associated mutation of CEP90 causes defective centriole duplication, similar to depletion of CEP90 or of MCPH proteins such as CDK5RAP2, CEP152, WDR62 or CEP63." (PMID 26297806, 2015). "Many genes have been implicated in the development of microcephaly (summarized inTable 1) includingASPM,MCPH1,CDK5RAP2,CEP152,CENPJ,WDR62,STIL,CASC5,CEP135,ZNF335,PHC1,CDK6, with many of them contributing to centrosome and spindle protein dysfunction during mitosis." (PMID 26535115, 2015). "To determine whether estradiol could regulate the seven currently known microcephaly genes (ASPM, CENPJ, CEP152, CDK5RAP2, MCPH1, STIL and WDR62), we conducted a search of the potential ERE (estrogen response element) sites in gene promoter regions." (PMID 26123139, 2015).
Seckel syndrome (20 papers, 2012 to 2025). A rare autosomal recessive inherited syndrome caused by mutations in the ATR gene, RBBP8 gene, CENPJ gene, CEP152 gene, CEP63 gene, NIN gene, DNA2 gene, or TRAIP gene. "The other is the CEP152 gene at chr15:49044671 with a variant of NM_001194998.1 c.3346–5T>C relevant to two diseases—primary microcephaly type and Seckel syndrome." (PMID 41306914, 2025). "The CEP152 gene at chr15:49044671 with a variant of c.3346–5T>C relevant to primary microcephaly type and Seckel syndrome." (PMID 41306914, 2025). "Here, we present genetic evidence by trio-WES where biallelic pathogenic variants in CEP152 causing Seckel syndrome 5 were detected." (PMID 36685824, 2022). "Nevertheless, it is worth noting that CENPJ and CEP152 have been also linked with Seckel syndrome, while CEP63, which has been primarily implicated in Seckel syndrome, is also linked to MCPH." (PMID 33946187, 2021). "Variants in CEP152 are a rare cause of MCPH but a frequent cause of Seckel syndrome." (PMID 41306914, 2025). "The CEP152 gene is associated with primary autosomal recessive microcephaly (MCPH) and Seckel syndrome (SCKS)." (PMID 41306914, 2025). "Mutations in CEP152 are a rare cause of MCPH; however, they are a frequent cause of Seckel syndrome." (PMID 33946187, 2021). "Seckel syndrome is caused by mutations in DNA damage response signaling and centriole biogenesis factors (ATR, ATRIP, CEP152, CENPJ)." (PMID 28630177, 2017). "More recently (January 2011-February 2014), mutations in for example RBBP8, CEP152 and DNA2 were found to cause Seckel syndrome: SCKL2, October 2011; SCKL5, January 2011; SCKL8, February 2014, respectively." (PMID 26919047, 2016). "The lack of Cep152 can cause centrosome duplication to fail.CEP152mutates, causing several diseases such as Seckel syndrome-5 and primary microencephaly-9." (PMID 38229970, 2024). "CEP152 mutations may cause two distinct PM phenotypes, i.e., the MCPH phenotype or the MPD phenotype resembling Seckel syndrome." (PMID 37443841, 2023). "Seckel syndrome is genetically heterogeneous, and mutations in DDR genes (ATRIP and ATR), DNA repair factors (NSMCE2, DNA2, TRAIP and CtIP) and components of the centrosome (NIN, CEP63, CEP152 and CENPJ) have been reported." (PMID 32994318, 2020). "Nine genes are associated with Seckel syndrome, of them 2 (CENPJ and CEP152) could cause both MCPH and Seckel syndrome." (PMID 29504900, 2018). "Interestingly, two genes associated with primary microcephaly, CEP152 and CENPJ have also been associated with the microcephalic primordial dwarfism family of disorders, a group of conditions with global growth failure." (PMID 28334956, 2017). "In contrast to cells from ATR-, CtIP-, CEP152- and PCNT-Seckel syndrome patients, we have shown that MEFs from Cenpj-deficient mice are not impaired in ATR-dependent DNA damage signaling but instead show an elevated frequency of extra centrioles, multipolar spindles, and near tetraploid karyotypes." (PMID 23166506, 2012). "Some genes can actually be responsible for either nonsyndromic PM or Seckel syndrome, such as CENPJ and CEP152, required for centriole biogenesis and centrosomal function." (PMID 35456440, 2022). "Ten genes have been reported for Seckel syndrome so far, and four of them (CENPJ, CEP152, CDK5RAP2 and CEP63) are also involved in MCPH." (PMID 34068194, 2021).
Primary microcephaly (7 papers, 2013 to 2026). Head circumference below 2 standard deviations below the mean for age and gender at birth. "CEP152 is essential for centriole function and neurodevelopment, and pathogenic recessive variants in CEP152 cause primary microcephaly." (PMID 42086905, 2026). "Centrosome function is crucial during embryonic development, highlighted by the discovery of mutations in genes encoding centrosome or spindle pole proteins that cause autosomal recessive primary microcephaly, including Cep63 and Cep152." (PMID 23936128, 2013). "Mutations in CEP152 have been associated with primary microcephaly; SHC4 is mainly expressed in the testes and brain; and EID1 may play a crucial role in lipid accumulation and proliferation of neural stem cells." (PMID 35440892, 2022). "Primary microcephaly (MCPH) associated proteins CDK5RAP2, CEP152, WDR62 and CEP63 colocalize at the centrosome." (PMID 26297806, 2015). "To date, mutations in nine genes encoding centrosome proteins have been identified in patients with primary microcephaly including some that are required for centriole duplication: STIL, CPAP, Cep152, Cep63 and Cep135." (PMID 23936128, 2013).
Autosomal primary recessive microcephaly (6 papers, 2013 to 2025). "Autosomal primary recessive microcephaly (MCPH) is a disorder in neurogenesis caused by at least nine genes, six of which encode centrosome components (CEP63, CEP135, CEP152, CDK5RAP2/Cnn, CPAP /MCPH6, and STIL/MCPH7) and two encode proteins associated with spindle poles (ASPM and WDR62)." (PMID 30687396, 2018).
ZIKV infection (2 papers, 2022 to 2023). "The functions of several mitosis-associated proteins, CEP152 and pericentrin (centrosomal), CENPJ (centromere) and TBK1 kinase (centrosomal) are affected during ZIKV infection, leading to mitotic defects and premature differentiation or cell death." (PMID 35412344, 2022).
Encephalopathy (1 paper, 2023). Encephalopathy is a term that means brain disease, damage, or malfunction. "For example, PAVS contains a disease-associated variant of the CEP152 gene known as NM_014985.3:c.2148-17 G>A and reported with “Encephalopathy” (HP:0001298)." (PMID 37479972, 2023). "Searching “CEP152 AND Encephalopathy ” for the relevant titles or abstracts in PubMed returns zero hits (search performed on 25 April 2022)." (PMID 37479972, 2023).
parathyroid disease (1 paper, 2025). "Among these, several genes such as APC, CEP152, CREBBP, FAM111A, FGFR1, KL and MMP14 have been previously suggested to be associated with parathyroid disease." (PMID 40434298, 2025).
prostate carcinoma (1 paper, 2015). A carcinoma that arises from epithelial cells of the prostate gland. "Another study evaluating this region for prostate cancer identified an interaction between rs12418451 and rs784411 in CEP152, a centrosomal protein shown to function as a regulator of genomic integrity and cellular response to DNA damage." (PMID 25789475, 2015).
cancer (3 papers, 2012 to 2023). A tumor composed of atypical neoplastic, often pleomorphic cells that invade other tissues. "Notably, various mutations in Cep63 and Cep152 are associated with the development of diverse human diseases, including cancer and microcephaly." (PMID 30858376, 2019). "Furthermore, since mutation of each of the five known Seckel genes, ATR, PCNT, CENPJ, CEP152 and RBBP8 (CtIP), cause genomic instability that is associated with apoptosis, it is possible that Seckel cells may not have the opportunity to accumulate cancer-causing mutations." (PMID 23166506, 2012).
CEP152 also shares sentences with these, for which no sentence is quoted: genetic diseases (2 papers); Primordial dwarfism (2); Seckel syndrome 5 (2); autism spectrum disorder (1); autosomal recessive mental retardation type 13 (1); autosomal recessive primary microcephaly-9 (1); ciliopathy (1); Compton-North congenital myopathy (1); Duchenne muscular dystrophy (1); dwarfism (1); generalized epilepsy with febrile seizures plus type 9 (1); hereditary spastic paraplegia (1); lung carcinoma (1); muscular dystrophy (1); polymicrogyria (1).